RN7SL541P (RNA, 7SL, cytoplasmic 541, pseudogene)
Gene: Miscellaneous RNA gene on chromosome 5 (134,517,810 to 134,518,092, forward strand). Ensembl gene ENSG00000240250.
Homologues: Orthologues: chimpanzee Metazoa_SRP (98% identical). Paralogues in human: RN7SL2 (70% identical), RN7SL1 (70% identical), RN7SL5P (70% identical), RN7SL4P (69% identical), RN7SL296P (69% identical), RN7SL3 (69% identical), RN7SL543P (69% identical), RN7SL480P (68% identical), RN7SL617P (68% identical), RN7SL122P (67% identical), RN7SL128P (67% identical), RN7SL218P (67% identical), and 701 more.